NUMBL (NUMB like endocytic adaptor protein)
Description:
Plays a role in the process of neurogenesis. Required throughout embryonic neurogenesis to maintain neural progenitor cells, also called radial glial cells (RGCs), by allowing their daughter cells to choose progenitor over neuronal cell fate. Not required for the proliferation of neural progenitor cells before the onset of embryonic neurogenesis. Also required postnatally in the subventricular zone (SVZ) neurogenesis by regulating SVZ neuroblasts survival and ependymal wall integrity. Negative regulator of NF-kappa-B signaling pathway. The inhibition of NF-kappa-B activation is mediated at least in part, by preventing MAP3K7IP2 to interact with polyubiquitin chains of TRAF6 and RIPK1 and by stimulating the 'Lys-48'-linked polyubiquitination and degradation of TRAF6 in cortical neurons.
Synonyms: Numb-R; CTG3a; CAG3A; TNRC23; NUMBR; NUMBLIKE; NBL
Tractability: PROTAC: its protein half-life has been measured.
Gene: Protein-coding gene on chromosome 19 (40,665,905 to 40,690,972, reverse strand). Ensembl gene ENSG00000105245.
Subcellular location: Cytoplasm
Gene Ontology:
Molecular function: protein binding
Biological process: cytokine-mediated signaling pathway; protein metabolic process; lateral ventricle development; nervous system development; neuroblast division in subventricular zone; positive regulation of neurogenesis; positive regulation of dendrite morphogenesis; regulation of postsynapse assembly
Cellular component: cytoplasm; glutamatergic synapse
Genetic constraint (gnomAD): Loss-of-function variants: 16 observed, 39.06 expected, observed/expected ratio (o/e) 0.41, 90% interval 0.28 to 0.62. The upper end of that interval is the gene's LOEUF score, 0.62, which puts it in group 2 of 6, group 1 being the genes least tolerant of losing a copy. Missense variants: 603 observed, 715.11 expected, observed/expected ratio (o/e) 0.84, 90% interval 0.79 to 0.9. Synonymous variants: 314 observed, 295.96 expected, observed/expected ratio (o/e) 1.06, 90% interval 0.97 to 1.16.
Homologues: Orthologues: chimpanzee NUMBL (100% identical), macaque NUMBL (99% identical), pig NUMBL (96% identical), mouse Numbl (95% identical), rat Numbl (94% identical), guinea pig NUMBL (94% identical), rabbit NUMBL (93% identical), dog NUMBL (93% identical), tropical clawed frog numbl (63% identical), zebrafish numbl (59% identical), Drosophila melanogaster numb (36% identical), Caenorhabditis elegans num-1 (33% identical), and 8 more. Paralogues in human: NUMB (55% identical), DAB2 (18% identical), DAB1 (16% identical), LDLRAP1 (11% identical), NOS1AP (11% identical), FAM43A (10% identical), MAPK8IP2 (9% identical), MAPK8IP1 (9% identical), FAM43B (8% identical), GULP1 (4% identical), C1orf226 (3% identical).
Diseases named in the same sentence as NUMBL in open-access papers:
NUMBL is named in the same sentence as 35 diseases in open-access papers, as found by Europe PMC text mining. Sharing a sentence is not in itself a finding about the gene and the disease. The quoted sentences say what the papers report.
lung carcinoma (4 papers, 2015 to 2024). "Another potentially interesting candidate is Numb Homolog (Drosophila)-Like (NUMBL) which encodes a protein that maintains progenitor cells during cortical neurogenesis and has previously been implicated in lung cancer." (PMID 26407342, 2015). "In lung cancer cell lines, the suppression of NumbL has been reported to promote cell proliferation." (PMID 36834720, 2023). "NumbL was reported to be downregulated in lung cancer cell lines; its ectopic expression suppresses proliferation and invasion, increasing apoptosis." (PMID 27613838, 2016). "To evaluate the potential role of NumbL promoter methylation in lung cancer, we analyzed the methylation status of the cluster in human lung tissue." (PMID 27613838, 2016). "Similarly, polarity protein NUMBL expressed in normal neural progenitor cells maintains progenitor-like characteristics in lung cancer by inhibiting KLF4, and restores KLF4 expression level can destroy progenitor cell subsets, thereby inhibiting the growth of lung cancer cells." (PMID 39695175, 2024).
glioma (3 papers, 2016 to 2021). A benign or malignant brain and spinal cord tumor that arises from glial cells (astrocytes, oligodendrocytes, ependymal cells). "Another report suggests that NUMBL regulates glioma cells migration and invasion by inhibiting TRAF5-induced NF-κB activation." (PMID 28974699, 2017). "In glioma cells NUMBL has been reported as a suppressor of TRAF5 mediated NF-κB activation." (PMID 28974699, 2017). "Similarly, in human glioblastoma cells, the overexpression of NumbL suppressed, while the elimination of NumbL promoted the migration and invasion of glioma cells." (PMID 27613838, 2016).
breast tumor (2 papers, 2016 to 2021). "When we specifically selected the relapsed tumors, those with low levels of NumbL had a worse prognosis, at least in breast tumors; the relapses were both local and at distant sites." (PMID 27613838, 2016). "In clinical breast tumor samples, NUMBL is downregulated, and the absence of NUMBL induces tumor cell chemoresistance for targeted therapy." (PMID 34374886, 2021).
colorectal cancer (2 papers, 2019 to 2024). A primary or metastatic malignant neoplasm that affects the colon or rectum. "In addition to the neuronal context, the induction of NUMBL showed inhibition of cell proliferation and even induction of tumor cell apoptosis in colorectal cancer." (PMID 31801555, 2019). "Zhang analyzed the role of Numb in tumor by searching literature with various software, suggesting that in colorectal cancer, NUMBL inhibits Notch pathway in colorectal tumor with unchanged NUMB expression, and the decrease in NUMBL expression leads to increased malignancies and poor prognosis." (PMID 39691600, 2024).
colorectal tumor (2 papers, 2016 to 2024). "Furthermore, low levels of NumbL decrease sensitivity to chemotherapy and correlate to a worse prognosis in breast, lung and colorectal tumors." (PMID 27613838, 2016). "Furthermore, we reported that, perhaps as a consequence of the activation of a CSC-like phenotype, low levels of NumbL decrease sensitivity to chemotherapy and are correlated with a worse prognosis in breast, lung and colorectal tumors." (PMID 27613838, 2016).
lung adenocarcinoma (2 papers, 2016 to 2018). A carcinoma that arises from the lung and is characterized by the presence of malignant glandular epithelial cells. "Again, the opposite happen for NUMBL probe cg20525355, being tumoral samples lower methylated regarding normal samples in colon adenocarcinoma (61% vs. 94.7%) and lung adenocarcinoma (75.8% vs. 100%)." (PMID 29507685, 2018). "Our data show a significant methylation of the NumbL promoter in lung adenocarcinoma tumors compared to non-tumor lung samples." (PMID 27613838, 2016).
non-small cell lung carcinoma (2 papers, 2014 to 2018). A group of at least three distinct histological types of lung cancer, including non-small cell squamous cell carcinoma, adenocarcinoma, and large cell carcinoma. "Overexpression of NUMBL has been associated with carcinogenesis and correlates with poor survival in metastatic non-small cell lung cancer." (PMID 24498427, 2014). "Transfection of A549 NSCLC (non-small cell lung cancer) cells with miR-296-5p was found to inhibit the mRNA and protein expression of NumbL." (PMID 30134788, 2018).
Arthritis (1 paper, 2017). Inflammation of a joint. "Since NUMBL expression is normally decreased or low under normal OC differentiation, it will be interesting to determine the expression and regulation of NUMBL in other pathological models of osteolysis such as arthritis." (PMID 28974699, 2017).
astrocytomas (1 paper, 2018). "In accordance with this hypothesis, NUMB levels are higher in astrocytomas and cervical squamous carcinoma cells, and the positive effect of NUMBL over SHH signaling can also promote tumor progression." (PMID 29507685, 2018).
cutaneous squamous cell carcinoma (1 paper, 2025). "A 2019 study identified a fusion between ADCK4 and NUMB-like endocytic adaptor protein (NUMBL) in cutaneous squamous cell carcinoma (cSCC), suggesting a potential oncogenic or tumor-modulating role." (PMID 40565246, 2025).
diabetes (1 paper, 2023). "Although there were no significant changes in the expression levels between the controls (HbA1C levels < 5.7%) and patients with diabetes, there was a surprisingly significant decrease in NumbL between the control and pre-diabetic groups." (PMID 36834720, 2023). "Further, we measured the NumbL mRNA levels in primary islets from patients with pre-diabetes (HbA1c level between 5.7–6.4%) and T2D (HbA1C levels > 6.4%)." (PMID 36834720, 2023). "However, more investigations are warranted to validate NumbL as a therapeutic target to treat diabetes." (PMID 36834720, 2023).
endometrial cancer (1 paper, 2025). Primary or metastatic malignant neoplasm involving the endometrium (mucous membrane that lines the endometrial cavity). "A study using the Cancer Genome Atlas (TCGA) examined NUMB and its homolog NUMBL across multiple tumor types, including endometrial cancer, and found that NUMBL expression was associated with poorer prognosis." (PMID 40296944, 2025).
kidney cancer (1 paper, 2021). Primary or metastatic malignant neoplasm involving the kidney. "While only weak correlation was uncovered between BCL2L13 and the known kidney cancer related genes, we found that voltage-dependent L-type calcium channel subunit beta-1 (CACNB1) and numb-like protein (NUMBL) are the two BCL2L13 negatively correlated genes." (PMID 34193180, 2021).
ovarian carcinoma (1 paper, 2024). A malignant neoplasm originating from the surface ovarian epithelium. "To explore potential drugs targeting patients in the GMPI‐high group, we collected four ovarian cancer samples and calculated GMPI for each sample with the following formula: GMPI = 0.090* KIAA0100 + 0.043* ANKRD27 + 0.215* OPA3 + 0.171* NUMBL + 0.314* PDP1–0.233*SLC7A11–0.007* TRMT112." (PMID 38506093, 2024).
paraganglioma (1 paper, 2023). A benign or malignant neoplasm arising from paraganglia located along the sympathetic or parasympathetic nerves. "Furthermore, significant up-regulation of NUMBL was also found in CHOL, ESCA, HNSC, kidney renal clear cell carcinoma (KIRC), kidney renal papillary cell carcinoma (KIRP), LIHC, LUAD, LUSC, THYM, PAAD, and pheochromocytoma and paraganglioma." (PMID 37657045, 2023).
renal cell carcinoma (1 paper, 2022). "The research about the functional roles of NUMBL and WDR62 in renal cell carcinoma is seldom." (PMID 36159976, 2022).
sarcoma (1 paper, 2016). A usually aggressive malignant neoplasm of the soft tissue or bone. "Here we show that NumbL knockdown increases tumorigenic properties in three different cancer cell lines of different origins, cervix HeLa, breast T47D and sarcoma AX, due to Notch pathway activation by stabilizing NICD." (PMID 27613838, 2016). "Finally, we decided to downregulate NumbL in a low passaged sarcoma cell line, AX." (PMID 27613838, 2016).
schizophrenia (1 paper, 2019). A major psychotic disorder characterized by abnormalities in the perception or expression of reality. "The authors found that only SNPs in the NUMBL gene, which also resides within cluster 1, have an association with schizophrenia." (PMID 31784692, 2019).
squamous cell lung carcinoma (1 paper, 2016). A carcinoma arising from squamous bronchial epithelial cells. "The same significant NumbL methylation profiles were observed in squamous cell lung cancer." (PMID 27613838, 2016).
uterine corpus endometrial carcinoma (1 paper, 2023). A endometrial carcinoma (disease) that involves the body of uterus. "Besides, genetic alternations of NUMB and NUMBL focused on uterine corpus endometrial carcinoma, and higher genetic mutations of NUMBL were correlated with more prolonged overall survival and disease-free survival in different cancers." (PMID 37657045, 2023).
tumor (10 papers, 2016 to 2025). "We showed that only that the downregulation of only NUMB or NUMBL causes an increment in the tumorigenic properties of cells, allowing us to focus on their roles as tumor suppressor genes." (PMID 29507685, 2018). "Our data are consistent with previous work indicating that NumbL downregulation is associated with a higher tumorigenic potential in lung and glioma cancer cell lines and its role as a tumor suppressor." (PMID 27613838, 2016). "We have found that NUMB and NUMBL exhibit mutual exclusivity in human tumors, suggesting that the associated tumor suppressor role is regulated by only one of the two proteins in a specific cell, avoiding duplicate signaling and simplifying the regulatory network." (PMID 29507685, 2018). "The knockdown of ADCK4 and NUMBL expression resulted in a mild reduction in cellular proliferation, implying a possible role in tumor growth regulation." (PMID 40565246, 2025). "Then the links between NUMB/NUMBL and tumor pathogenesis were further explored, containing differential gene expression, pathological features, prognostic survival, genetic mutation, protein phosphorylation, and relative cellular pathway." (PMID 37657045, 2023). "Meanwhile, the remarkably differences of NUMBL phosphorylation levels between tumor and normal controls appeared in 4 types of primary tumors (KIRC, LUAD, COAD, and UCEC)." (PMID 37657045, 2023). "Using the GEPIA, the correlations between the mRNA levels of NUMB/NUMBL with patients individual tumor stages of different cancers from TCGA were compared." (PMID 37657045, 2023). "Unexpectedly, the analysis of expression level of NUMBL between tumor and normal tissues shows that dysregulation of NUMBL emerges in 27 of 33 tumor types of TCGA data library, more extensive than NUMB." (PMID 37657045, 2023). "Next, we determined the genes that correlated to NUMB or NUMBL in all considered tumor types and then compared the individual tumor types to obtain a map of common genes correlating to NUMB or NUMBL expression in various tumors." (PMID 29507685, 2018). "Genes such as CFLAR, EP300, GBP2, HEYL, KLF7, NOTCH1 or POFUT showed a similar correlation with NUMB or NUMBL in the three tumor types considered." (PMID 29507685, 2018). "Here, we showed that NUMB and NUMBL presented mutual exclusivity in tumors, suggesting that the tumor suppressor effect on the Notch pathway is regulated by one protein at a time, thus simplifying the regulatory network." (PMID 29507685, 2018). "We found 675 genes that were positively correlated and 691 genes that were negatively correlated to NUMBL in at least three of the considered tumor types." (PMID 29507685, 2018). "NUMBL has also been described as a tumor suppressor gene, mainly based on its ability to inhibit the Notch pathway." (PMID 29507685, 2018). "NUMB and NUMBL have been considered tumor suppressor genes with very similar functions because both can regulate the Notch pathway." (PMID 29507685, 2018). "NUMB and NUMBL are commonly described as proteins with a very similar function, characterized as tumor suppressors." (PMID 29507685, 2018). "A plausible explanation is that the tumors with downregulated NumbL have a larger number of cancer stem cells that avoid the action of the chemotherapy, thus providing an advantage for tumor relapse." (PMID 27613838, 2016). "The methylation profile of NumbL was evaluated in human tumor samples and compared to non-tumor tissue using the Illumina Infinium Human Methylation 450 BeadChip." (PMID 27613838, 2016). "In summary, our data help to clarify the role of NumbL in tumorigenesis, suggesting that NumbL acts as a tumor suppressor regulating the Notch pathway, EMT and CSC-like phenotype, and thus contributing to resistance to chemotherapy and worse prognosis." (PMID 27613838, 2016).
tumor (continued). "NumbL knockdown is sufficient to induce cancer stem cell-like transcription and phenotypic properties, suggesting an important role as a tumor suppressor gene by maintaining the CSC-like phenotype through Notch pathway activation." (PMID 27613838, 2016). "To fully confirm the role of NumbL as a tumor suppressor acting on the Notch pathway and stem cell gene transcription, we decided to overexpress NumbL cDNA into these three cell lines and assess transcription and behavior." (PMID 27613838, 2016). "Our data support the idea of NumbL as a tumor suppressor, sharing this phenotype with its related Numb." (PMID 27613838, 2016). "To further confirm the role of NumbL as a tumor suppressor, we overexpressed NumbL cDNA into these cells." (PMID 27613838, 2016). "Besides, using the GEPIA dataset, top 100 genes in all tumor expression data of TCGA that correlated with NUMB- or NUMBL were gathered respectively." (PMID 37657045, 2023). "What is more, these data suggested that NUMB/NUMBL might play crucial roles in the tumor progression of different cancers from TCGA." (PMID 37657045, 2023). "Similarly, the downregulation of NUMBL in tumor cells can also induce Notch activation, leading to an increase in epithelial to mesenchymal transition (EMT) and the cancer stem cell-like pool." (PMID 34374886, 2021). "However, our analysis showed that NUMB and NUMBL exhibited almost independent correlations when we considered the four tumor types." (PMID 29507685, 2018). "Thus, although both NUMB and NUMBL are considered tumor suppressors, an increment in the expression of at least NUMB cannot be assumed to lead to an increase in a tumor suppressor gene due to the observed alternative splicing." (PMID 29507685, 2018). "Therefore, NumbL can act as an independent tumor suppressor inhibiting the Notch pathway and regulating the cancer stem cell pool." (PMID 27613838, 2016). "Our results strongly support a tumor suppressor role for NumbL." (PMID 27613838, 2016). "Although we found that the increase in this tumorigenic phenotype related to CSCs is related to Notch pathway activation, it is possible that other pathways may also contribute to the activity of NumbL as a tumor suppressor." (PMID 27613838, 2016). "Similarly, NUMBL also acts as both tumor suppressor and activator in various types of malignancies." (PMID 37657045, 2023). "However, when we compared the genes that were correlated to NUMB or NUMBL in each individual tumor type, we found common positively or negatively correlated genes, suggesting that NUMB and NUMBL participate in different gene regulatory processes, depending on the tissue." (PMID 29507685, 2018). "Our previous data strongly suggest that NumbL may behave as a tumor suppressor in human tissue." (PMID 27613838, 2016). "NUMBL and PHF21A were upregulated but PDGFRA was downregulated in tumor samples compared with normal samples in the Human Protein Atlas (HPA) database." (PMID 38167072, 2024). "We also demonstrated that high expression of NUMBL and PHF21A, but low expression of PDGFRA in tumor tissues compared with normal tissues." (PMID 38167072, 2024). "We have recently showed that NUMBL behaves, such as NUMB, its close relative, as a tumor suppressor gene regulating the Notch pathway." (PMID 29507685, 2018). "A comparison of each tumor type allowed us to identify a small number of genes that were equally related to NUMB and NUMBL, different genes related to similar functions, and genes with differential expression." (PMID 29507685, 2018). "In order to explore the association between protein phosphorylation and oncogenicity, the differences in NUMB/NUMBL phosphorylation levels between primary tumor tissues and normal tissues were compared." (PMID 37657045, 2023). "However, many of the genes correlating with NUMBL showed an opposite behavior with NUMB in the other two analyzed pathways, WNT and Hedgehog, independently of the type of tumor." (PMID 29507685, 2018).